GOLGA6L1 (golgin A6 family like 1)
Tractability: No criterion of Open Targets' tractability assessment is met for any kind of drug.
Gene: Protein-coding gene on chromosome 15 (23,127,066 to 23,136,822, reverse strand). Ensembl gene ENSG00000273976.
Genetic constraint (gnomAD): Loss-of-function variants: 0 observed, 0.93 expected, observed/expected ratio (o/e) 0, 90% interval 0 to 1.74. That is too few expected variants to judge how well the gene tolerates losing a copy. Missense variants: 2 observed, 12.18 expected, observed/expected ratio (o/e) 0.16, 90% interval 0.066 to 0.52. Synonymous variants: 2 observed, 2.27 expected, observed/expected ratio (o/e) 0.88, 90% interval 0.33 to 1.85.
Homologues: Paralogues in human: GOLGA6L26 (96% identical), GOLGA6L6 (94% identical), GOLGA6L22 (94% identical), GOLGA6L24 (91% identical), GOLGA6L25 (91% identical), GOLGA6L2 (46% identical), GOLGA6L7 (41% identical), GOLGA6L4 (21% identical), GOLGA6L10 (21% identical), GOLGA6L9 (18% identical).